ICAM1 (intercellular adhesion molecule 1)
Diseases named in the same sentence as ICAM1 in open-access papers (continued):
Sharing a sentence is not in itself a finding about the gene and the disease.
infection (continued). "Positive vascular ICAM-1 immunostaining at levels comparable to those observed in ODC-OVA mice was also observed in VE-Cadherin-GFP control mice, suggesting that even at day 7 post LCMV-OVA infection and complete clearance of the LCMV virus the BBB still retains a mild inflammatory phenotype." (PMID 37253744, 2023). "TNF signaling also stimulates the production of adhesion molecules, such as intercellular adhesion molecule-1 (ICAM-1) and vascular cell adhesion molecule-1 (VCAM-1), which allow immune cells to adhere to and traverse the endothelial barrier to reach the site of infection." (PMID 37511508, 2023). "We observed that the number of ICAM1+ monocytes in the blood during 1/148 infections increased 25-fold compared to the non-infected control and 4-fold compared to IL3000 infections (two-way ANOVA with Tukey’s Multiple Comparison Test, p-value = 0.0002 and 0.0131)." (PMID 35787830, 2022). "After infection with HRV-B14 from ATCC (titer unknown) and four subsequent passages, two HRV-B14 batches were obtained with a titer of 6.8 and 6.3 log10 CCID50/mL for Vero_ICAM1#4C4 and Vero_ICAM1#9G4, respectively." (PMID 36298792, 2022). "Interestingly, the introduction of α4 blocking mAb prior and during early phases of infection did not inhibit neutrophil recruitment to infected lungs of either WT or ICAM-1/2-/- mice in a statistically significant manner." (PMID 36895258, 2022). "Infection with type I parasites non-significantly impacted ICAM-1 expression in DCs." (PMID 35990682, 2022). "Furthermore, ICAM-1, which was differentially upregulated in HIBCPP cells in all examined conditions after infection, also serves as a signalling receptor transducing outside signalling such as leukocyte adhesive interactions with intracellular epithelial and endothelial function." (PMID 34863201, 2021). "In addition to chemotaxis, adhesion molecules such as ICAM-1, CD11b, and CD44 could be mediating CCR2+Ly6C+ monocyte trafficking to sites of infection as it was shown in the liver of primary Lm-infected mice." (PMID 34516896, 2021). "In addition, expression of ICAM-1, which is required for the migration of leukocytes from the blood into infected tissue, was significantly lower in male compared to female lungs early after HN878 infection." (PMID 32198367, 2020). "Strikingly, HIV-1 virions that display ICAM-1 in their outer membrane were found to be more infectious (2- to 9-fold) than virions without ICAM-1, and activation of cellular LFA-1 enhanced infection with ICAM-bearing viruses by over forty-fold in both cell lines and PBMC." (PMID 30669528, 2019). "Furthermore, directly HCMV-infected mDCs, exhibiting viral gene expression, strongly adhere to fibronectin and ICAM-1, in contrast to mDCs lacking infection or viral gene expression." (PMID 28484459, 2017). "Finally, LFA-1 on the B cell and ICAM-1 on the epithelial cell are important for mediating EBV infection of epithelial cells; in fact, blocking LFA-1 or ICAM-1 with antibodies reduces the efficiency of infection." (PMID 29202043, 2017). "To analyze the role of ICAM-1, a major ligand for LFA-1, we used ICAM-1 KO mice and challenged them with blood trypomastigotes of the Y strain of T. cruzi, which did not affect the susceptibility of these mice to infection." (PMID 29081775, 2017). "Similarly, pretreatment and treatment of the cells before and after infection with vehicle of EM900 did not change ICAM-1 mRNA expression after infection." (PMID 26462747, 2015). "Thus, pretreatment of the cells with vehicle did not affect ICAM-1 mRNA expression prior to infection." (PMID 26462747, 2015).
infection (continued). "Hence, we could see that the brain endothelium in all co-infected mice stained more intensely for both ICAM-1 and VCAM compared to all other infection modalities under the same conditions." (PMID 25075973, 2014). "Our in vivo data demonstrating significant increase of ICAM-1, VCAM-1 and E-selectin in the brain at day 8 after infection correlates with the peak of inflammatory cytokines levels and suggest that this may be one of the downstream responses of virus-induced inflammation in the brain." (PMID 25036379, 2014). "The lack of effect on ICAM-1 expression, the receptor for rhinovirus, and on IL-8 release, the potent chemotactic factor for neutrophils (that are already present in sites of infection), may represent protective functions." (PMID 23663325, 2013). "Furthermore, pre-incubation of the cells with blocking antibodies to LFA-1 or ICAM-1 also reduced the efficiency of transfer infection by 60 to 70%, whilst antibodies to αVβ6 integrin had no significant affect on the efficiency of transfer infection." (PMID 21573183, 2011). "Because the cells harvested at six days post-infection persisted in culture as non-adherent cells, we chose to investigate surface expression of the adhesion markers intercellular adhesion molecule-1 (ICAM-1, CD54) and vascular cell adhesion molecule-1 (VCAM-1, CD106)." (PMID 18787698, 2008). "Up-regulation of adhesion molecules like intercellular adhesion molecule 1 (ICAM-1) or vascular cell adhesion molecule-1 (VCAM-1) in pulmonary epithelium was observed after exposure to diverse stimuli such as LPS, outer membrane protein A from K. pneumoniae or infection with P. carinii." (PMID 16827942, 2006). "Indeed, the evolutionarily conserved pyrogenic response to infection is known to stimulate the immune response partly by promoting lymphocyte transendothelial migration across HEVs via increased luminal display of CCL21 (and ICAM1) under the influence of IL6 trans-signaling." (PMID 41216593, 2025). "ICAM-1 and its receptor LFA-1 are involved in the syncytium formation induced in the co-culture of HTLV-1-positive and HTLV-1-negative human T-cell lines, suggesting that induction of ICAM-1 by Tax may facilitate infection of HTLV-1 from the virus-producing cells to uninfected cells." (PMID 41153438, 2025). "Therefore, on the one hand, we have observed the acute death of mice post infection, and on the other hand, we have also demonstrated the BBB disruption as well as neuroinflammatory disorder of dead or dying animals in this acute period, in which both PDGF-BB and ICAM-1 do play important roles." (PMID 31092253, 2019). "Therefore, the changes in RV14 RNA and ICAM-1 mRNA expression after RV14 infection might not be affected by changes in mRNA expression of β-actin, which was used as a housekeeping gene in the present study." (PMID 26462747, 2015). "K13-induced upregulation of adhesion molecules and MHC-1 molecules during natural infection with KSHV may be modulated by concomitant expression of viral lytic proteins, such as the K5 gene product and vIRF1, which have been shown to down-regulate the expression ICAM-1 and MHC-I molecules." (PMID 19660139, 2009). "Here, we verified the effect of LOV on these mediators and observed that treatment prevented the increase in ICAM-1 levels, but VCAM-1 and MCP-1 levels were not affected by either infection or treatment." (PMID 38785783, 2024). "Pom did not substantially increase B7-2 or ICAM-1 surface expression in the uninfected BL41- cells even at 5 or 10 μM Pom, or the cellular B7-2, suggesting that infection of the cells is required for the effects of Pom in BL lines." (PMID 37463943, 2023). "Seven days after infection (MOI of 0.1), replication of HRV-B14 was observed in both Vero_ICAM1 cell lines (Vero_ICAM1#4C4 and Vero_ICAM1#9G4), but not in the parental Vero cell line." (PMID 36298792, 2022).
infection (continued). "At the cellular level, proteins like ICAM-1, TLR2 or Ezrin/Radixin were only up-regulated in CACs treated with the serum of asymptomatic patients at the highest peak of infection (PCR + /IgG −), but not with the serum of PCR −/IgG + individuals." (PMID 35397534, 2022). "As CVA21 is incapable of utilizing mouse ICAM-1, YUMM 2.1 cells were used as a negative control for the infection." (PMID 34503272, 2021). "Anti-ICAM-1 antibodies specifically inhibited RV89 infection up to a dilution of the antibodies of 1:2500, whereas no inhibition of infection was observed with the normal rabbit antibodies at any dilution." (PMID 32570763, 2020). "On the other hand, P. aeruginosa significantly increased the expression of two possible cell receptors for S. aureus, i.e., ICAM-1 and ITGA-5 (marker for integrin α5β1) in lung tissue, while mono-infections by S. aureus did not." (PMID 31921058, 2019). "Whilst the mock-infected HBMVE cells did not exhibit any staining of E-selectin and ICAM-1, a very strong signal was observed in WNV-infected HBMVE at day 3 after infection." (PMID 25036379, 2014). "There are contradictory data, however, that not all LFA-1 ligands play this role, as ICAM-1 and ICAM-3 have not been confirmed to be involved in HIV-1 trans infection." (PMID 24278768, 2013). "Fibronectin and vitronectin reproducibly inhibited infection in these experiments by up to 40%, whilst LAMB1, ICAM-1, VCAM-1 or heparan sulphate did not affect the efficiency of infection." (PMID 21573183, 2011). "It is worth noting that infection of endothelial cells with KSHV results in down-regulation of MHC class I, PE-CAM (CD31), and ICAM-1 (CD54), but not LFA-3 (CD58) or Fas (CD95), and the viral genes K3 and K5 have been demonstrated to regulate this outcome." (PMID 18787698, 2008). "However, our screening also identified invasion- and migration-related genes that were not significantly modulated upon infection (i.e., PAPPA, SNAIL, MMP9, MMP11, ICAM1, CTNNB1, and CDH2)." (PMID 41450565, 2025). "Similarly, ICAM-1 (CD54), the canonical binding partner of CD11a/CD18, does not contribute to pulmonary recruitment during infection." (PMID 35646729, 2022). "Furthermore, we observed that leukocytes also expressed increased ICAM1 (fivefold) and ICAM2 (twofold), but not VCAM1, upon infection with either strain." (PMID 35787830, 2022). "The finding that ICAM1 is upregulated in wild type, but not in TLR4−/− eyes, correlates with our previous findings that neutrophil recruitment is decreased in TLR4−/− eyes following infection." (PMID 29661181, 2018). "However, it was also reported that there was no significant change in ICAM-1 cell surface expression in HUVEC after 24 h and 48 h infection as detected by horseradish peroxidase reaction." (PMID 28750011, 2017). "PBS controls exhibited baseline staining for ICAM-1, as well as classical staining patterns for IBA1+ professional phagocytes and GFAP, a marker expressed exclusively in astrocytes in the CNS; mice at day 2 of infection had no overt pathological changes." (PMID 28742087, 2017). "As compared to the mock-infected controls, the mRNA transcripts of ICAM-1, VCAM-1 and E-selectin in the brain did not change at day 4 after infection (data not shown), however a 2- to 9-fold increase was observed at day 6, which further increased at day 8 after infection." (PMID 25036379, 2014). "Consequently, blocking of ICAM-1-LFA-1 interactions between mDC and non-activated primary CD4+ T cells substantially reduced the productive mDC-mediated HIV-1 trans-infection of CD4+ T cells." (PMID 23590845, 2013). "Notably, ICAM-1 and VCAM-1 signal were detected in infected mice in regions both with and without T. gondii parasites, indicating a global effect of infection on endothelial cell activation, likely due to systemic inflammation-induced upregulation of these adhesion molecules." (PMID 39780244, 2025).
infection (continued). "A multivariate model containing 5,6-dihydroxyeicosatrienoic acid, 8,9-dihydroxyeicosatrienoic acid, intercellular adhesion molecule-1, interleukin-6, and interleukin-8, could differentiate patients with VAP from brain injured patients without infection (AUROC 0.94 (0.80–1.00))." (PMID 30283005, 2018). "In order to determine whether adherence to ICAM-1 or to CD36 and the involvement of SMAC was applicable to other rodent malarias, the effect of the lack of these molecules on a P. chabaudi blood-stage infection of C57BL/6 mice was investigated." (PMID 28468674, 2017). "However, through the use of an in vitro model of polarized primary epithelial cells, we showed that transfer infection could be demonstrated only via the basolateral surface, and did not involve LFA-1/ICAM-1 interactions." (PMID 21573183, 2011).
inflammation (97 papers, 2011 to 2025). Aberrant reaction of the microcirculation characterized by movement of fluid and leukocytes from the blood into extravascular tissues. "Endothelial P-selectin and ICAM-1 are major adhesion molecules that are highly overexpressed during acute pancreatic inflammation and their blockade has been associated with reductions in pancreatic and lung damage." (PMID 32019239, 2020). "ICAM-1 enables leukocytes to migrate through the endothelia to the inflammation site, participates in immunological synapse formation, and it is also implicated in the formation and progression of atherosclerotic lesions and development of experimentally induced intestinal inflammation." (PMID 28265273, 2017). "As a critical vascular adhesion molecule, ICAM-1 mediates the recruitment of leukocytes from circulation into sites of renal inflammation and plays a fundamental role in immune cell signaling and activation." (PMID 41394867, 2025). "Several studies have shown that airway inflammation is characterised by an up-regulation of ICAM-1 on airway epithelium, which is of particular importance to the induction of antigen or viral-induced airway inflammation." (PMID 39598462, 2024). "In turn, NF-κB regulates the expression of ICAM-1, a cell surface glycoprotein that plays a pivotal role in the recruitment of leucocytes at the sites of intestinal inflammation." (PMID 38543230, 2024). "In the context of pancreatic inflammation, they upregulate the expression of key adhesion molecules, most notably P-selectin and intercellular adhesion molecule 1 (ICAM-1)." (PMID 39595191, 2024). "One of the causes explaining the defective antiviral response during allergic inflammation is the upregulated expression of intercellular adhesion molecule 1 (ICAM-1), the receptor for major group RVs, leading to an increased susceptibility to RV infection." (PMID 36769047, 2023). "During vascular inflammation, the expression of adhesion molecules, including ICAM-1, VCAM-1, and E-selectin, is elevated, promoting leukocyte recruitment to the endothelium." (PMID 34925018, 2021). "Serum levels of C-reactive protein (CRP), E-selectin, and ICAM-1 (circulating markers of vascular inflammation), which were higher in irradiated control IgG-treated mice than in non-irradiated mice, were also significantly reduced by Ab417 treatment." (PMID 34078883, 2021). "Down-regulation of iCAM1 and iCAM5 genes is also an important finding, as the levels of iCAM1 were shown to be elevated in sera of PF patients, and recent studies showed that iCAM-1 inhibition reduced exacerbations of lung inflammation." (PMID 33465050, 2021). "To analyze endothelial inflammation, we then measured the transcript level of endothelial inflammatory cell adhesion molecule ICAM1 in cells exposed to the differential high glucose challenge." (PMID 34685528, 2021). "To further illuminate the mechanisms that underlie the impact of TNF-α on lung inflammation/injury, we also examined and found mir-331-3p suppressed the expression of inflammation-associated genes MCP-1, VCAM-1, and ICAM-1 in vitro and in vivo." (PMID 33072088, 2020). "In the BE3C system, which is the model of lung inflammation, intercellular-adhesion molecule-1 (ICAM1) was negatively affected by both sulphated reticulines, but not affected or affected only slightly in the culture treated with (S)-reticuline." (PMID 29789647, 2018). "Curcumin supplementation ameliorates diabetic vascular inflammation through the decrease in ROS overproduction and ICAM-1 expressions." (PMID 27527213, 2016). "Future studies should focus on the long-term efficacy of the inhibition of ICAM-1 on the pathophysiological changes of bladder inflammation with respect to all involved signaling pathways in NBC rats." (PMID 27782122, 2016). "Hyperglycemia-induced ROS can stimulate NF-κB activation which then causes the increase in vascular adhesion molecule expression (ICAM-1), which plays a central role in diabetic vascular inflammation." (PMID 27527213, 2016).